GEMIN2 (gem nuclear organelle associated protein 2)
Description:
The SMN complex catalyzes the assembly of small nuclear ribonucleoproteins (snRNPs), the building blocks of the spliceosome, and thereby plays an important role in the splicing of cellular pre-mRNAs. Most spliceosomal snRNPs contain a common set of Sm proteins SNRPB, SNRPD1, SNRPD2, SNRPD3, SNRPE, SNRPF and SNRPG that assemble in a heptameric protein ring on the Sm site of the small nuclear RNA to form the core snRNP (Sm core). In the cytosol, the Sm proteins SNRPD1, SNRPD2, SNRPE, SNRPF and SNRPG (5Sm) are trapped in an inactive 6S pICln-Sm complex by the chaperone CLNS1A that controls the assembly of the core snRNP. To assemble core snRNPs, the SMN complex accepts the trapped 5Sm proteins from CLNS1A. Binding of snRNA inside 5Sm ultimately triggers eviction of the SMN complex, thereby allowing binding of SNRPD3 and SNRPB to complete assembly of the core snRNP. Within the SMN complex, GEMIN2 constrains the conformation of 5Sm, thereby promoting 5Sm binding to snRNA containing the snRNP code (a nonameric Sm site and a 3'-adjacent stem-loop), thus preventing progression of assembly until a cognate substrate is bound.
Synonyms: SIP1; SIP1-delta
Tractability: PROTAC: ubiquitination databases record sites on it; its protein half-life has been measured.
Gene: Protein-coding gene on chromosome 14 (39,114,285 to 39,139,037, forward strand). Ensembl gene ENSG00000092208.
Subcellular location: Nucleus, gem; Cytoplasm
Subcellular location (Human Protein Atlas): Nuclear bodies; Nucleoplasm; Nucleoli
Pathways (Reactome):
Disease: SARS-CoV-2 modulates host translation machinery
Metabolism of RNA: snRNP Assembly
Gene Ontology:
Molecular function: protein binding
Biological process: protein-containing complex assembly; spliceosomal snRNP assembly; mRNA processing; RNA splicing; RNA splicing, via transesterification reactions; spliceosomal complex assembly
Cellular component: cytosol; Gemini of Cajal bodies; nuclear body; SMN complex; SMN-Sm protein complex; nucleoplasm; nucleus; cytoplasm; spliceosomal complex
Genetic constraint (gnomAD): Loss-of-function variants: 5 observed, 5.01 expected, observed/expected ratio (o/e) 1, 90% interval 0.51 to 1.8. That is too few expected variants to judge how well the gene tolerates losing a copy. Missense variants: 74 observed, 65.13 expected, observed/expected ratio (o/e) 1.14, 90% interval 0.94 to 1.38. Synonymous variants: 28 observed, 28.43 expected, observed/expected ratio (o/e) 0.98, 90% interval 0.73 to 1.35.
Homologues: Orthologues: chimpanzee GEMIN2 (100% identical), macaque GEMIN2 (100% identical), dog GEMIN2 (96% identical), mouse Gemin2 (94% identical), rat Gemin2 (94% identical), pig GEMIN2 (93% identical), rabbit GEMIN2 (93% identical), guinea pig GEMIN2 (87% identical), tropical clawed frog gemin2 (77% identical), zebrafish gemin2 (66% identical), Drosophila melanogaster Gem2 (29% identical), Caenorhabditis elegans smi-1 (25% identical).
Diseases named in the same sentence as GEMIN2 in open-access papers:
GEMIN2 is named in the same sentence as 5 diseases in open-access papers, as found by Europe PMC text mining. Sharing a sentence is not in itself a finding about the gene and the disease. The quoted sentences say what the papers report.
HIV-1 infection (1 paper, 2008). The type species of lentivirus and the etiologic agent of acquired immunodeficiency syndrome (AIDS). "The Hamamoto report used siRNA to downregulate Gemin2 and SMN in cells subsequently infected by HIV-1, showing that disruption of these proteins blocked HIV-1 infection, and Gemin2 disruption reduced viral DNA copy number, 2-LTR circle accumulation, and proviral integration." (PMID 18554410, 2008).
spinal muscular atrophy (1 paper, 2020). A motor neuron disease that affect the muscles, and characterized by muscle weakness and atrophy resulting from progressive degeneration and irreversible loss of the anterior horn cells in the spinal cord (i.e., lower motor neurons) and the brain stem nuclei. "Moreover, the deficiency of SMN causes human neurodegenerative disease spinal muscular atrophy (SMA), and knockdown of Gemin2 causes motor neuron degeneration in zebrafish and depresses motoric abilities in Drosophila, emphasizing the pathophysiological relevance of the Sm-core assembly pathway." (PMID 31799625, 2020).
tumor (2 papers, 2022 to 2023). "Meanwhile, the expression of PALLD and GEMIN2 in the tumor was obviously lower than that in tumor-adjacent tissue." (PMID 36421795, 2022). "CDKN2A, GEMIN2, DLAT, and ZCRB1 were expressed at higher levels in tumors than in normal tissues, while the expression of KLF9 in tumor tissue was lower." (PMID 36909185, 2023).
infection (1 paper, 2009). The state of being infected such as from the introduction of a foreign agent such as serum, vaccine, antigenic substance or organism. "Thus, Gemin2 is required for an early event post-infection that affects early reverse transcription product (negative strand strong stop) less than later products or integrated DNA, suggesting that Gemin2 associates with either the reverse transcription or pre-integration complexes." (PMID 21994574, 2009).
GEMIN2 also shares sentences with these, for which no sentence is quoted: osteoporosis (1 paper).